PIK3CA (phosphatidylinositol-4,5-bisphosphate 3-kinase catalytic subunit alpha)
Diseases named in the same sentence as PIK3CA in open-access papers (continued):
Sharing a sentence is not in itself a finding about the gene and the disease.
leukemia (21 papers, 2012 to 2025). A malignant (clonal) hematologic disorder, involving hematopoietic stem cells and characterized by the presence of primitive or atypical myeloid or lymphoid cells in the bone marrow and the blood. "Although PI3K deletion prolonged survival in the KMT2A-MLLT3 AML model, Pik3ca – deleted mice eventually still develop leukemia with a similar phenotype as control WT;Mx1-Cre mice." (PMID 40791365, 2025). "To determine whether Pik3ca is also required to maintain functional leukemia-initiating cells (LICs), we performed secondary transplantation of decreasing doses of GFP+ leukemic cells from the primary transplant recipients into sub-lethally irradiated mice." (PMID 40791365, 2025). "We analyzed the expression of the PIK3CA, AKT1, and mTOR genes across various leukemia cell lines using the Human Protein Atlas database, with a specific focus on the HL-60 cell line, which was employed in our study." (PMID 40917720, 2025). "We then attempted to achieve a preliminary exploration of the pathogenesis of leukemia through the study of five prognostic genes (TNF, CXCR3, CD4, PIK3CA and CALR)." (PMID 38671491, 2024). "SuperDendrix also identifies increased dependencies on PIK3CA and BCL2 in some of the same cancer types, including PIK3CA in myeloma and rhabdomyosarcoma and BCL2 in leukemia and myeloma." (PMID 35382456, 2022). "miR-375 possesses significant anti-leukemia or anti-tumor activity through modulating multiple target genes, including JAK2, SP1, PIK3CA, and AEG-1." (PMID 29439669, 2018). "Activating PIK3CA mutations are exceedingly uncommon among pediatric cancers (< 1 % of leukemias and solid tumors and < 3 % of brain tumors), and the PPTC panel of approximately 240 models has none with activating PIK3CA mutations (St." (PMID 39510293, 2024). "In the case of PIK3CA amplification on DNA level in the context of lymphoma or leukemia, the related literatures were scarce and rather limited, not to mention in DLBCL." (PMID 29029507, 2017).
stomach cancer (21 papers, 2005 to 2025). "The PIK3CA-gene is of interest because about 15% of the stomach tumors present with a mutation observed predominantly in the EBV-positive molecular subgroup." (PMID 39323992, 2024). "It is indeed possible that a tumor sample taken from the core of a gastric tumor shows a PIK3CA mutation, while a sample from the invasive front exhibits a wild-type status for the gene." (PMID 38392195, 2024). "Our findings are in keeping with previous reports showing that gastric tumors with high PD-L1 expression levels frequently harbor PIK3CA mutations." (PMID 30670970, 2018). "Activating mutations of PIK3CA are found most commonly in tumors of the stomach, colorectum, brain, breast, liver, ovaries, and lung." (PMID 25834816, 2015). "Using mass spectrometry-based genotyping we analysed 105 hotspot, non-synonymous somatic mutations in PIK3CA and ERBB-family (EGFR, ERBB2, ERBB3 and ERBB4) genes in gastric tumour samples from 69 patients." (PMID 33933113, 2021). "In conclusion, we have identified two genes, cMET and PIK3CA, and 6 miRNAs, miR-223-3p, miR-19a-3p, miR-128-3p, miR-130b-3p, miR-34a-5p and miR-124-3p that were statistically differently expressed in gastric tumor tissues compared with normal mucosa." (PMID 26334097, 2015). "PIK3CA mRNA and protein expression were reported to be significantly higher in gastric tumor tissues compared to normal gastric adjacent mucosa." (PMID 26334097, 2015). "PIK3CA c.3140 is a known somatic hotspot location in many cancer types, including gastric tumors." (PMID 34075207, 2021). "The fact that only one type of mutation was found in our series of MSI tumors is not surprising as the narrow spectrum of alterations of MSI gastric tumors may, in turn, restrict the type of PIK3CA mutations that are oncogenic in that context." (PMID 20398348, 2010). "Integrated analysis of public data from gastric tumors revealed frequent (10 – 20 %) amplification of the genes NFKBIE, PTK2, and PIK3CA, each of which resides in an ERBB2-derived subpathway network." (PMID 26955870, 2016). "Normal gastric mucosa and gastric tumor tissues were compared for ARID1A, CDH1, c-MET and PIK3CA mRNA expression using RT-qPCR." (PMID 26334097, 2015). "Increased PIK3CA expression level was observed in gastric tumours compared with non-neoplastic mucosae." (PMID 15784156, 2005).
endometrial tumors (20 papers, 2012 to 2025). "In particular, aberrant PI3K signaling is frequently seen in human malignancies as shown by the detection of oncogenic PIK3CA mutations in colon, brain and other cancer types, including breast and endometrial tumors." (PMID 34062774, 2021). "Molecular characterization of endometrial tumors has demonstrated that PIK3CA mutations, PTEN loss, and PI3K and KRAS activation are key events in carcinogenesis." (PMID 32754300, 2020). "Second, PIK3CA mutations appear to be highly clonal in endometrial tumors as described in a recent high throughput sequencing study investigating spatial genetic relationships in the primary-metastasis setting." (PMID 28860563, 2017). "Since PIK3CA is another frequently mutated gene in endometrial tumors, PIK3CA-directed inhibitors may show benefits but its utility is still under investigation." (PMID 37483495, 2023). "Somatic mutations in PIK3CA and KRAS frequently co-occurred in colorectal, lung, head and neck, gastric and endometrial tumors." (PMID 32087721, 2020). "Mutation co-occurrence occurred frequently with PIK3CA and KRAS genes in lung, colorectal, head and neck, gastric and endometrial tumors." (PMID 32087721, 2020). "Furthermore, those patients that have endometrial tumors that are PTEN-negative, or carry mutations in the PIK3CA gene, could be considered for combinatorial MK-2206 and progestin therapy." (PMID 22911820, 2012). "In contrast, high PIK3CA mRNA levels were observed in non-endometrioid tumors, which would appear to be consistent with previous findings linking PIK3CA gene amplification to aggressive endometrial tumors of non-endometrioid histology." (PMID 28002804, 2017). "Interestingly, our prior study of samples from the Caris database indicated that in post-menopausal women, endometrial tumors harboring the CC genotype were enriched with multiple genomic alterations in the PI3 kinase pathway, including PTEN, PIK3CA, and PIK3R1." (PMID 40282446, 2025). "Genes with co-alterations notably enriched in KRASm subsets included STK11 in non-Sq NSCLC, PIK3CA and APC in CRC, and ARID1A, PTEN, and PIK3CA in endometrial tumors." (PMID 36494601, 2022).
serous carcinoma (20 papers, 2008 to 2025). "The mutation of KRAS/BRAF was observed in Western countries, whereas PIK3CA mutation was the main driver for Japanese low-grade serous carcinoma progression." (PMID 35621684, 2022). "In high-grade serous carcinoma patients, PIK3CA copy number gain was more prevalent than PIK3CA mutation." (PMID 33947352, 2021). "PTEN (82% vs. 15%, p < 0.01) and PIK3CA (74% vs. 23%, p < 0.01) mutations were more frequent in endometrioid than serous carcinomas." (PMID 33256706, 2020). "It was possible to distinguish high grade serous carcinomas with BRCA1 mutations from those with epigenetic BRCA1 loss: tumours with BRCA1 mutations typically had decreased PTEN mRNA levels while those with epigenetic loss of BRCA1 had copy number gain of PIK3CA." (PMID 18208621, 2008). "In contrast, PIK3CA and KRAS were altered by mutations in those histological subtypes, in contrast to high-grade serous carcinomas (P = 0.002 and P = 0.0495, respectively)." (PMID 33947352, 2021). "BRCA1/2 alterations, PTEN loss, and gain of PIK3CA and CCND1 were characteristic for high-grade serous carcinomas." (PMID 33947352, 2021). "At the molecular genetic level, low-grade serous carcinomas are characterized by frequent somatic sequence mutations in genes that are involved in signal transduction including KRAS, BRAF, ERBB2, and PIK3CA." (PMID 22028712, 2012).
Proteus syndrome (19 papers, 2014 to 2025). Proteus syndrome (PS) is a very rare and complex hamartomatous overgrowth disorder characterized by progressive overgrowth of the skeleton, skin, adipose, and central nervous systems. "It is a cardinal feature of several overgrowth disorders as with the Beckwith–Wiedemann spectrum (BWSp), Proteus syndrome and many of the clinical entities related to somatic pathogenic variants in PIK3CA (PIK3CA-Related Overgrowth Spectrum, PROS)." (PMID 34944785, 2021). "In the differential diagnosis of PIK3CA-related disorders, it is important to consider other syndromes with overlapping characteristics but different genetic causes, such as Proteus syndrome and PTEN Hamartoma Tumor Syndrome." (PMID 34238334, 2021). "Other sporadic disorders caused by somatic mosaic events rather than germline mutations include activating mutations of AKT1 associated with Proteus syndrome and gain of function mutations in PIK3CA causing macrodactyly." (PMID 24497998, 2014). "Somatic activating mutations in the PI3K/AKT/mTOR pathway are among the most common mutations identified in cancer and have been shown to cause a spectrum of overgrowth syndromes including PIK3CA-Related Overgrowth Spectrum, Proteus syndrome, and brain overgrowth conditions." (PMID 40406354, 2025). "Somatic overgrowth conditions, including Proteus syndrome, Sturge–Weber syndrome, and PIK3CA‐related overgrowth spectrum, are caused by post‐zygotic pathogenic variants, result in segmental mosaicism, and give rise to neural, cutaneous and/or lipomatous overgrowth." (PMID 30761771, 2019). "Similar to PIK3CA, somatic mutations in AKT may also manifest as isolated lesions or within a complex syndromic phenotype, the Proteus syndrome." (PMID 38747293, 2024). "An open label, Phase 1/2 study of miransertib administered to subjects at least 2 years of age with PROS and Proteus syndrome (PS) is currently underway to more accurately assess the efficacy of miransertib in the treatment of PIK3CA-related overgrowth spectrum disorder." (PMID 33639990, 2021). "In the 20 patients with isolated macrodactyly who did not meet the diagnostic criteria for Proteus syndrome, we identified and confirmed pathogenic variants in PIK3CA." (PMID 33054853, 2020). "In particular, the PIK3CA inhibitor BYL719 and the AKT inhibitor ARQ092 are in clinical trials for patients with PROS and Proteus syndrome." (PMID 32350708, 2020).
serous ovarian cancer (19 papers, 2008 to 2025). "In serous ovarian cancer, PIK3CA amplification is highly frequent but PIK3CA point mutation is rare." (PMID 39543937, 2024). "Even though alterations in the RAS and PIK3CA pathways are mostly related to low-grade serous ovarian carcinomas, we were able to detect mutations in those genes in 14.3% and 15% of young and elderly HGSOC, respectively." (PMID 34944094, 2021). "The USP13 gene is co-amplified with PIK3CA in 29.3% of high-grade serous ovarian cancers and its overexpression is significantly associated with poor clinical outcome." (PMID 27892457, 2016). "Together, this study reveals the molecular pathways driven by the PIK3CA aberrations and the exploitable vulnerabilities in PIK3CA-aberrated serous ovarian cancer cells." (PMID 39543937, 2024). "Compared with other histologic subtypes, OCCC exhibits higher prevalence of PIK3CA mutations and PTEN deletion (20–46% and 20%, respectively, compared with 2.3–3.7% and 7%, respectively, in high-grade serous ovarian carcinoma)." (PMID 34737943, 2021). "USP13 is co-amplified with PIK3CA in high-grade serous ovarian cancer." (PMID 32974170, 2020). "Cell lines with PIK3CA H1047R had a significantly lower mean LN(IC50) in the cancer-type-non-specific setting; however, this category encompassed several cancer types, including BRCA, HNSC, and ovarian serous carcinoma (OV)." (PMID 30053901, 2018).
Hyperglycemia (18 papers, 2017 to 2026). An increased concentration of glucose in the blood. "Given these constraints and nuances like PIK3CA mutation-site biology and class-specific toxicities (e.g., hyperglycemia with PI3Kα inhibitors), future trials should enrich for HPV-independent histotypes." (PMID 41155343, 2025). "It is noteworthy that the majority of the trials excluding patients with diabetes involve PIK3CA or mTOR inhibitors, both of which are known to cause hyperglycemia." (PMID 38778365, 2024). "IRS-1 interacts with the catalytic p110 subunit, leading to increased PIP3 and p85 regulatory subunit sequestration, which is associated with increased insulin resistance and can explain the side effects of PIK3CA inhibitors, such as hyperglycemia." (PMID 38396649, 2024). "The commencement of inavolisib, a small molecule designed to selectively inhibit mutant PIK3CA, immediately resulted in grade 3 hyperglycemia that persisted despite the commencement of metformin and insulin glargine." (PMID 39437820, 2024). "Hyperglycemia was one of the most frequent AEs found with PIK3CA inhibitors, with rates equal to 64% in SOLAR-1, 43% in BELLE-2, 37% in BELLE-3, and 40% in the SANDPIPER trial." (PMID 36900211, 2023). "Despite the differences in hyperglycemia incidence and management in SOLAR-1, similar median PFS was observed among high- and low-risk patients with PIK3CA mutations treated with alpelisib + fulvestrant (median PFS, 11.0 vs 10.9 months; HR, 1.097; 95% CI, 0.733–1.641)." (PMID 38439079, 2024). "The phase 3 SOLAR-1 trial of alpelisib, a PIK3CA inhibitor, demonstrated hyperglycemia as the most common adverse event occurring in 63.7% of patients, with grade 3 or 4 hyperglycemia (blood glucose level (BGL) >250 mg/dL or 13.9 mmol/L) observed in 36.6% of patients." (PMID 39437820, 2024). "Hyperglycemia is the most common adverse event within the PI3K inhibitor class of medication and occurred in 63.7% of patients treated with alpelisib, a PIK3CA inhibitor, in the SOLAR-1 trial." (PMID 39437820, 2024). "While all our patients received standard pre-medication with dexamethasone, we did not see a hyperglycemia rate higher than that used in the SOLAR-1 trial, which combined alpelisib with fulvestrant in patients with advanced PIK3CA-mutated hormone-positive breast cancer." (PMID 36923283, 2022).
invasive ductal carcinoma (18 papers, 2015 to 2025). "Compared with wild-type PIK3CA tumors, PIK3CA-mutated tumors were significantly more prevalent in the upper outer quadrant of the breast and were more commonly associated with Invasive ductal carcinoma." (PMID 40472482, 2025). "We analyzed a TCGA patient (TCGA-A2-A04P) diagnosed with breast invasive ductal carcinoma with an oncogenic somatic mutation in PIK3CA." (PMID 37207338, 2023). "In conclusion, we demonstrate that almost 50% of ER-positive, HER2-negative early invasive ductal carcinoma of the breast had mutations of PIK3CA gene." (PMID 29707142, 2018). "Although histologic subtypes other than invasive ductal carcinoma are scarcely represented in our study, we could identify PIK3CA mutations in triple negative invasive lobular carcinoma, medullary carcinoma, and even in special variants of BC, as adenoid cystic carcinoma." (PMID 26540293, 2015). "We note that PIK3CA double mutations are relatively more dominant in BRCA, IDC (Breast Invasive Ductal Carcinoma), ILC (Breast Invasive Lobular Carcinoma), COAD, and UEC (Uterine Endometrioid Carcinoma) subtypes." (PMID 36808143, 2023). "Mutations in the PIK3CA gene are found at similar frequencies in pure ductal carcinoma in situ, ductal carcinoma in situ adjacent to invasive ductal carcinoma (IDC), and in IDC, suggesting that PIK3CA mutations are key to shaping the tumor identity at the initial steps of tumorigenesis." (PMID 40676433, 2025). "Comparing mutation carriers and non-carriers, PIK3CA mutation carriers were significantly more likely to be ER-positive (P = 0.041), PR-positive (P = 0.004) and invasive ductal carcinoma (IDC) (P = 0.002)." (PMID 30212483, 2018). "Alas, most publications on breast MEC do not provide significant information on genetic testing performed, PIK3CA alterations are widely detected in the invasive ductal carcinoma population and its triple‐negative subtypes." (PMID 36916425, 2023).